IL13 (interleukin 13)
Diseases named in the same sentence as IL13 in open-access papers (continued):
Sharing a sentence is not in itself a finding about the gene and the disease.
Allergy (continued). "The current study was aimed to study the association of IgE and different variants of Interleukin-4 (IL-4), and Interleukin-13 (IL-13) genes with different kind of allergies." (PMID 34814942, 2021). "Expression of allergy-associated cytokine genes, including Il4, Il5, Il9, Il13, and Il21, was higher in Nr4a-TKO cells, even when compared with Foxp3-KO cells." (PMID 33665581, 2021). "Both the IL-4 and IL-13 pathways play roles in the inflammation associated with allergies; however, they also play fundamental roles in cellular function." (PMID 34948449, 2021). "Our study suggests that increased IgE levels and in association with variant forms of IL-4 and IL-13 genes are significantly associated with different types of allergies in study population." (PMID 34814942, 2021). "For instance, prenatal allergen-specific Th-2 responses, particularly IL-13 responses, have been associated with atopic risk or subsequent allergic diseases." (PMID 34485278, 2021). "Interleukin IL-5, IL-4, and IL-13 and innate (ILC-2) lymphoid cells that can maintain and enhance local TH2 inflammation caused by the secretion of TH2 cytokines (IL-13 and IL-5) are the primary cytokines responsible for the allergic response." (PMID 34831860, 2021). "The hallmark of clinical allergy is the development of allergen-reactive T helper 2 (Th2) cells, which produce Type 2 cytokines (IL-4, IL-5, IL-13) that promote Ig isotype switch in B cells." (PMID 34305927, 2021). "Antigen-specific Th2 cells cause allergic diseases, such as asthma, rhinitis, and atopic dermatitis, by producing Th2 cytokines (IL-4, IL-5, and IL-13)." (PMID 33662037, 2021). "Similar to allergies, helminth infections induce a Th2 immune response associated with cytokines such as interleukin (IL)-4, IL-5, IL-9, IL-13, and increased levels of eosinophils, basophils, mast cells and circulating IgE Abs." (PMID 32268573, 2020). "These n-3 PUFAs reduce the risk of developing allergic diseases and they have been shown to lower the acetylation of IL-13 genes." (PMID 31349704, 2019). "We aimed to study the expression of the Th2 cytokine (IL-4, IL-5, and IL-13) genes, which are implicated in allergic reactions, and changes in the actual secretion of the cytokines." (PMID 29772010, 2018). "The prevention of allergy is known to be associated with the downregulations of IL‐4, IL‐5, IL‐13 and IL‐10." (PMID 28165193, 2017). "The protein-coding genes listed were closely linked to allergy and associated with lncRNAs; moreover, some of them such as Il4, Il5, and Il13 were regulated by iPSC-MSC treatment, and therefore these lncRNAs were also associated with iPSC-MSC immunomodulation." (PMID 28057064, 2017). "The design of the synthetic mammalian cell-based dual TH2 cytokine sensor (DCS) device is based on a common IL-13 receptor (IL-13R) that is shared by the allergy-associated cytokines IL-4 and IL-13." (PMID 29062109, 2017). "In allergies, the presence of large amounts of some Th2-type cytokines, for example interleukin 13 (IL-13), can cause inflammatory signs such as mucous hypersecretion." (PMID 28248962, 2017). "SNPs and haplotypes in genes encoding IL-4, IL-4R, and IL-13 have been shown to play a critical role in allergy and IgE production." (PMID 27566584, 2016). "The levels of pro-inflammatory cytokines (IL-1β, IL-6, TNF), anti-inflammatory cytokine (IL-10), Th2-type cytokines associated with allergy (IL-4, IL-13, IL-33) and Th1-type cytokine (IFN-γ) were analysed from the treated skin sites of all groups." (PMID 25123235, 2014). "Levels of CD4+ IFN-γ+ (Th1), IL-13+ (allergy-associated Th2), as well as IL-17+ and IL-10+ (immunoregulatory) cells peaked at 72 hours in mice exposed to WT conidia and indicated a mixed Th1, Th2 and Th17 response." (PMID 25340353, 2014). "The association between cesarean delivery and AD was significantly modified by parental history of allergic diseases or risk-associated IL-13 (rs20541) and CD14 (rs2569190) genotypes." (PMID 24848505, 2014).
Allergy (continued). "It is well recognized that allergic diseases are closely associated with an enhanced Th2 immune response with high levels of IL-4, IL-5, and IL-13, but accumulating evidence also implicates down-regulated Th1 immune responses in the pathogenesis of allergy." (PMID 25090641, 2014). "In adipose tissue, eosinophil that migrates from the blood into adipose tissue, can produce IL-4 and IL-13, cytokines typically associated with the arm of the immune system that causes allergy but also protect against infection with parasites." (PMID 23894289, 2013). "In line with the known role of IL-13 in induction of Th2 responses, rs20541polymorphisms have also been linked to allergy and autoimmune disease as well as altered outcomes of helminth (Schistosome spp) infections." (PMID 23144702, 2012). "IL-13 has been linked to airway hyper responsiveness and mucous production in the same mouse model of allergy." (PMID 20552026, 2010). "In particular, IL-4 and IL-13 are involved in the isotype switch from IgM to IgE, the antibody responsible for classic allergy and implicated in the pathophysiology of allergic asthma." (PMID 20616938, 2010). "None of these results are definitive individually but taken together provide strong evidence that IL13 is a susceptibility gene for allergic disease." (PMID 18197984, 2008). "Other investigators have found further evidence for the role of IL13 polymorphisms in the pathogenesis of allergic disease." (PMID 18197984, 2008). "In contrast, interleukin-13 (IL-13) is a hallmark Th2 cytokine that promotes allergy development." (PMID 40944184, 2025). "Interestingly, the expression of IL-13 and IL-33, anti-inflammatory cytokines associated with allergic diseases, was also statistically upregulated in the pdr6Δ-infected mice relative to WT." (PMID 40444466, 2025). "Interestingly, the anti-inflammatory IL-10 and the allergy-associated cytokines, IL-9 and IL-13, were also significantly lower in FHL1−/− than WT mice at both time points." (PMID 37884534, 2023). "By contrast, clinical allergy is caused by dysregulated type 2 immunity, which is characterized by expansion of T helper 2 (Th2) cells and eosinophils, as well as overproduction of the associated cytokines IL-4, IL-5, IL-9, and IL-13." (PMID 35281022, 2022). "Obviously, genetic factors like special variants of the IL-4, IL-4R, and IL-13 genes may have a prominent role in development of allergy; therefore, their contribution should be carefully noticed." (PMID 35307016, 2022). "Importantly, type 2 inflammatory cytokines such as IL-4 and IL-13 are implicated in allergy and EoE." (PMID 36177009, 2022). "As IL-13 is implicated in allergic disease, NFAT is believed to be a reasonable therapeutic target." (PMID 36230993, 2022). "In allergic reactions and associated overproduction of mucus, IL-13 is implicated." (PMID 34943565, 2021). "Similar cytokine production effects were found with eicosapentaenoic acid (EPA) and arachidonic acid (AA), whereas linoleic acid (LA) increased OX40L surface expression and subsequent T-cell-derived IL-13/IFNγ ratios, suggesting an increased risk of allergy development." (PMID 32431702, 2020). "IgE is often associated with allergic diseases, and elevated IgE may be due to a response to elevated plasma IL-13 in allergic disease." (PMID 31649905, 2019). "The allergic reaction is associated with high levels of IgE and IL-13." (PMID 26968945, 2016). "Thus, basophils might represent an important source of Th2-like cytokines (IL-4 and IL-13) in the lung microenvironment, particularly that associated with human allergic disease." (PMID 36578500, 2022). "Another variant influencing total IgE levels in the Swedish population was IL13 rs20541, which has been associated with allergic phenotypes and helminth susceptibility in parasite exposed populations suggesting that this is a regulatory locus common to both allergy and parasite responses." (PMID 27977724, 2016).
Allergy (continued). "Allergy is a type I hypersensitivity reaction involving Th2 cells that produce Interleukin (IL)-4, IL-5, IL-9, and IL-13." (PMID 41596388, 2026). "The M2a subtype synthesizes cytokines such as IL-4, IL-10, and IL-13, playing a role in allergies, anti-inflammatory activity, and the induction of fibrosis." (PMID 41499529, 2026). "IgE is the immunoglobulin paradigm of allergy, with IL-4 and IL-13 as the main stimulators of IgE production." (PMID 41596388, 2026). "In a type I hypersensitivity allergic reaction, there is a Th2 immune response characterized by Th2 cells, eosinophils, basophils, IgE, IL-4, IL-5, and IL-13 serum elevation." (PMID 41596388, 2026). "The hallmarks of allergic diseases are Type 2 immunity, including IL-4 and IL-13 production, IgE antibody generation, mast cell and basophil activation, histamine release, and eosinophil activation." (PMID 42274577, 2026). "(d) Using a recently developed humanized CFTR mouse model, we demonstrated an in vivo ivacaftor-mediated decrease in allergy through reductions in type 2 cytokines (IL-5 and IL-13) and total serum IgE." (PMID 40131363, 2025). "Other studies suggest the possible involvement of the Th2 pathway in non-IgE-mediated allergies, with findings of elevated serum levels of cytokines such as IL-3, IL-5, and IL-13 in patients with this type of allergy." (PMID 41394805, 2025). "Cytokines involved in allergic inflammation, such as interleukin-4 (IL-4) and interleukin-13 (IL-13), play significant roles in driving the immune responses characteristic of allergic diseases." (PMID 40566616, 2025). "Th2 cells secrete proinflammatory cytokines, including IL-4, IL-13, IL-5, and IL-19, which amplify the inflammatory response and recruit effector cells responsible for releasing mediators of the allergic reaction." (PMID 41002407, 2025). "ILC2s and Th2 cells secrete IL-4, IL-5, and IL-13, which induce an inflammatory immune response that plays a key role in allergic reactions." (PMID 40290033, 2025). "NK cells proliferate in the presence of IL-4 and can contribute to the production of IL-4, IL-5, and IL-13 cytokines in an allergic reaction." (PMID 40718495, 2025). "Emerging therapies include recombinant cytokines, exosomes, and monoclonal antibodies targeting IL-4/IL-13 or IL-5, which are mostly approved for the treatment of allergic diseases." (PMID 41007770, 2025). "This is evidenced by the findings that IL-13 and its receptor IL-13RA1 are required for inflammatory response in a variety of allergy models in mice." (PMID 38399441, 2024). "The IL-4, IL-5, and IL-13 secreted by Th2 inhibit the activity of Th1 and stimulate B cells to produce IgG1 and IgE, and their secretion regulates the allergy-mediated Th1–Th2 balance, lymphocyte infiltration, and cytokine secretion." (PMID 38674852, 2024). "The AR response include high amounts of specific IgE in the serum, high amounts of allergy relative mediators (eosinophil peroxidase and tryptase), and Th2 cytokines (IL-4, IL-5, IL-13) in nasal secretions, and high total nasal symptom scores (TNSS)." (PMID 38783329, 2024). "These NAD+ metabolites also play a role in asthma and allergies through the activity of multiple inflammatory cytokines, including IL-13." (PMID 38399441, 2024). "The lung OVA-specific cytokine panel was expanded to include two additional allergy related cytokines mediators (IL-10, IL-13) in addition to the previously evaluated Th1/2 cytokines." (PMID 39108263, 2024). "These shrimp allergy-associated genes include HLA-DQ (rs9275596), HLA-DRB1 (HLA-DRB1*04:05-HLA-DQB1*04:01), IL-13 (rs20541, and IL13 rs1800925), and food allergy -associated gene TLR4 rs4986790 (Asp299Gly)." (PMID 39493746, 2024). "Dupilimab, also a mAb, allosterically inhibits IL4 and IL13, two TH2 cytokines that are implicated in allergy and IgE-mediated immune responses." (PMID 39493746, 2024).
Allergy (continued). "IL-12 and IL-13 are key pro-inflammatory cytokines involved in pathogenesis of allergy, cancer, and tissue fibrosis, and they are both elevated in RVO." (PMID 39272767, 2024). "Since IL-4 and IL-13 play important roles in the pathogenesis of allergic diseases, blocking both the IL-4 and IL-13 signals is a powerful and effective strategy for treating allergic diseases." (PMID 38731893, 2024). "These cells preferentially express Th2 cytokines, particularly IL-5 and IL-13, and have the potential to enhance local allergy induced by T2 inflammation." (PMID 39388827, 2024). "Similar to human allergic disease, canine allergy is characterized by increased expression of the type 2 cytokines IL-4, IL-5 and IL-13, e.g. in dogs with atopic dermatitis." (PMID 38835756, 2024). "Periostin has recently emerged as a promising biomarker of type 2 inflammation in allergic diseases, notably induced by signature type 2 cytokines like IL-4 and IL-13 or exacerbating their effects, thereby propagating allergic skin inflammation." (PMID 39722037, 2024). "Th2 cells induce the secretion of cytokines such as IL-4, IL-5, and IL-13, promoting the production of immunoglobulin (Ig) A and Ig E, thereby regulating humoral immune responses and allergic diseases." (PMID 39664894, 2024). "Th2 cells directly trigger the aggregation and activation of inflammatory cells by releasing IL-4, IL-5, IL-13, and other cytokines, and promote the occurrence of delayed airway allergic reactions." (PMID 38546350, 2024). "The type‐2 response entails the generation of Th2 cytokines, like IL‐4, IL‐5, and IL‐13, which trigger the production of non‐opsonizing antibodies and allergic reactions, while also suppressing the pronounced inflammatory response induced by Th1 cytokines." (PMID 38774871, 2024). "Recently, type 2 innate lymphoid cells (ILC2) have also been identified as one of the major producers of IL-4 and IL-13 in the development of allergic diseases." (PMID 39567378, 2024). "cTh2 cells mainly express IL-4 and IL-13, thereby promoting the B-cell class switch to IgE antibody-producing plasma cells in type I allergic reactions." (PMID 39076967, 2024). "The occurrence of an allergic response can stimulate the release of type 2 inflammatory mediators, including IL-4, IL-5, and IL-13, which promote the recruitment and activation of eosinophils, mast cells, and basophils, thereby inducing nasal eosinophilia." (PMID 38070374, 2024). "Eosinophils are the most potent immune cell during allergy and parasitic infections producing IL-4 and IL-13 cytokines." (PMID 37197738, 2023). "IL-4 and IL-13 are cytokines related to type 2 immunity, which mediates the immune response against helminths but is also intrinsically related to allergies." (PMID 37766239, 2023). "IL-13 is a Th2 cytokine in the immune system thought to play an important role in the development of allergies, although it has also been ascribed anti-inflammatory roles, inhibiting different pro-inflammatory mediators such as IL-1β and TNF-α." (PMID 37373554, 2023). "Here, we show that GJExCR treatment reduced the Th2-mediated immune response in OVA-induced allergy, including dampening of IL-4, IL-5, IL-10, IL-13, TNF-α, INF-γ, chemokine, and IgE expression, in both serum and spleens." (PMID 36980282, 2023). "Since IL4R and IL13 play major roles in IgE-mediated activation for allergy, they have been studied widely in different populations since 2004 and have become a promising therapeutic target for allergic reactions in recent years." (PMID 37780578, 2023). "In parallel, the role of IL-4 and IL-13 in the mast cell- and basophil-related context was widely documented by employing numerous human and mice models of allergy." (PMID 36675006, 2023). "High plasma IL-13 and IL-4 in patients with COVID-19 requiring intensive care indicates acute activation of the allergy cytokine pathway in this disease." (PMID 37040185, 2023).
Allergy (continued). "IL-13, on the other hand, tends to be more prevalent in sites of active allergy, and its production induces tissue alterations such as hyperplasia of goblet cells, mucus secretion, and fibrosis." (PMID 37766239, 2023). "IL-4 and IL-13 are members of the Th2-type cytokines and play a critical role in the type II inflammatory response triggered by allergy or parasite infection." (PMID 36985596, 2023). "It is well known that corticosteroids suppress the synthesis of Th2-derived cytokines (such as IL-4 and IL-13) necessary for the production of IgE, thus contributing to their effectiveness in controlling allergic diseases." (PMID 37514093, 2023). "Allergic diseases are dominated by systemic type 2 inflammation with overexpression of cytokines such as IL-4 and IL-13, which, in the skin, regulate the epidermal barrier and the effector phase of the immune response." (PMID 37753208, 2023). "In allergic reactions, allergens activate T cells to differentiate into Th2 cells and secrete IL-4, IL-5, and IL-13, leading to allergen-specific IgE production." (PMID 37101296, 2023). "HRF induces IL-4 and IL-13 production by changing the balance between Th1 and Th2 to a higher Th2 response, which is also a driver of allergic reactions." (PMID 37760889, 2023). "IL-13 is produced mainly by Th2 cells, shares many physiological functions with IL-4, and is a known factor in allergy pathogenesis." (PMID 36078882, 2022). "Tregs secrete regulatory cytokines such as and IL-10 and TGF-β, which reduce pulmonary eosinophil infiltration, allergy-specific Th2 cytokines (IL-4, IL-5, and IL-13), allergy specific IgG1 and IgE production, allergic rhinitis symptoms, and AHR." (PMID 36556359, 2022). "Type 2 immunity consists of GATA3+ Th2 cells and mediates allergy by producing IgE antibody as well as IL-4, IL-5, and IL-13." (PMID 35484967, 2022). "Of course, the leading role is played by the IL-4 and IL-13 genes involved in the development of inflammatory reactions during the exacerbation of allergies, including the work of regulatory T-cells of mucous membranes and skin." (PMID 35629280, 2022). "Alleviation of allergy symptoms is due mostly to the manipulation of proinflammatory cytokines secreted by mast cells, and IL-3, IL-4, and IL-13 are regarded as critical therapeutic targets in allergic inflammatory illnesses." (PMID 36142314, 2022). "Dupilumab represents an even more fundamental attack on allergic disease, suppressing IL-4 and IL-13 signaling required for not only IgE production, but the underlying Th2 response driving it." (PMID 36230993, 2022). "IL-4 and IL-13 are typical Th 2 cytokines; the former influences the secretion of IgE, while the latter can aggravate allergic reactions." (PMID 35163859, 2022). "In a prior study, CD34+ stem cells from blood donors express ST2L and produce IL-5 and IL-13 in response to IL-33 supporting these stem cells as potential effector cells in allergic diseases." (PMID 36177009, 2022). "We provide evidence that this is being driven by type 2 inflammation, demonstrated by IL-4/IL-13 and Th2 gene expression signatures and clinical allergic disease that dramatically responds to Jakinib therapy." (PMID 36546480, 2022). "Although few reports have been reported on allergic diseases, a recent study reported that Bex2 expression was suppressed by the increased DNA methylation of IL-13 which was induced in allergic airway inflammation." (PMID 36556359, 2022). "Through producing and secreting type 2 cytokines such as IL-4, IL-5 and IL-13, Th2 cells activate B cells to class-switch to IgE and incentive mast cells to release inflammatory mediators, leading to the occurrence of allergic diseases." (PMID 36713372, 2022). "When mast cells are activated, the pro-inflammatory cytokines such as IL-4 and IL-13, secreted from Th2 cells, activate B cells and generate an allergic reaction by producing IgE." (PMID 35889810, 2022).